CD4 (CD4 molecule)
Diseases named in the same sentence as CD4 in open-access papers (continued):
Sharing a sentence is not in itself a finding about the gene and the disease.
tumor (continued). "MOC1 tumor had significantly more non-regulatory CD4 T cells in the stroma, also, although statistically not significant, MOC1 had tendency to have smaller number of CD8 T cells and Tregs infiltrating into the tumor." (PMID 32937841, 2020). "CEA-TCB-treated tumors displayed a clear upregulation of several pro-inflammatory cytokines and chemokines [MIPα (CCL3), CXCL10, CXCL13, CXCL9, IL-16, and I-TAC (CXCL11)], an increase in intra-tumor CD3+, CD4+, CD8+ T-cells that express high levels of 4-1BB, PD-1, and upregulation of GZMB." (PMID 33330050, 2020). "Suppression of CD4+, but not CD8+ T cell proliferation was more pronounced when T cells were co-cultured with tumor-associated myeloid cells from ICB NR compared to R." (PMID 32071302, 2020). "Both CD4+ FOXP3+ and CD8+ FOXP3+ cells inhibit tumour rejection and promote tumour growth." (PMID 33276543, 2020). "Thus far, both CD4 and CD8 T cells have been shown critical for BCG-mediated anti-tumor activity and response in mouse models." (PMID 33584702, 2020). "In the tumor tissue profiles, significant positive correlations between immune metagenes and clinical stage or overall survival were observed among Natural Killer (NK) cells (CD56−), CD4+ T-helper 2 (Th2) cells, and activated Dendritic Cell (aDC)." (PMID 32580490, 2020). "Furthermore, type I IFN signaling was critical for accumulation of tumor-infiltrating CD8+ and CD4+ T cells, DCs, and macrophages following irradiation of B16 melanoma models." (PMID 33238631, 2020). "Mechanistically, multiplex quantification of CD3+/CD4+/CD8+ T cells and flow cytometry analysis showed that combined therapy favors tumor infiltration by CD8+ T cells, whilst in vivo CD8+ T cell depletion led to tumor growth restoration." (PMID 33126649, 2020). "Further study found that SYY and MS could increase the ratio of CD4+ to CD8+, but reduce the proportion of Treg and TGF-β1 expression in spleen, peripheral blood as well as tumor tissue." (PMID 32733246, 2020). "In particular, resting memory CD4 T cells and resting dendritic cells in healthy renal tissue were most common; whether CD8 T cells and macrophages were most frequent in tumor tissue." (PMID 33665156, 2020). "Therefore, we further analyzed the percentages of CD3+CD4+ cells and CD3+CD8+ cells in total T cells from the spleen and the tumor infiltrating lymphocytes." (PMID 32425796, 2020). "By contrast, in the tumour nests the CD8+ and FoxP3+ lymphocytes, and not the CD4+ and CD20+ cells, were significantly associated with survival, and only in the ER/PR positive patients." (PMID 32577938, 2020). "Firstly, the strong correlations between CD20+ and CD4+ cell densities, which were present in tumour samples but not in normal breast tissue, heavily suggest a combined mechanism of action for those cell types." (PMID 33153211, 2020). "Indeed, several studies using genomic and bioinformatics approaches to design personalized neoantigen vaccines report a strong neoantigen-specific anti-tumor CD4+ and CD8+ T cell response correlated with tumor control in mice and humans." (PMID 32290124, 2020). "This response was due to increased CD4+ and CD8+ T cell infiltration into the tumor tissues." (PMID 33207653, 2020). "DCs, as crucial APCs, mediate tumor immunity via the activation of CD8+ and CD4+ T cells." (PMID 32746880, 2020). "Adoptive transfer of PCK1-overexpressing T cells into the B16 murine melanoma model demonstrated improved production of CD4+ T cell derived IFN-γ and increased expression of the M1 macrophage CD86 marker on TAMs, collectively suppressing tumor growth and improving survival." (PMID 33324565, 2020). "Solanine may enhance the antitumor immune response by downregulating the proportion of CD4+CD25+ Treg and the expression of Foxp3 and TGFβ in tumor tissues." (PMID 33204731, 2020).
tumor (continued). "Interestingly, the most prevalent subtypes differed between locations, with CD4+ lymphocytes being the most prevalent in tumour stroma and at the tumour edge, while CD8+ lymphocytes were the most prevalent in tumour nests." (PMID 32577938, 2020). "To functionally confirm that the anti-tumor effects of Arf1-depletion in Lgr5/Apc and MYC-ON mice were indeed dependent on the observed adaptive immune response, we depleted the T lymphocytes after tumor formation by injecting anti-CD4 or anti-CD8 antibodies." (PMID 31924786, 2020). "Thus the anti-proliferative effect might curb solid tumor growth whereas the elimination of DTCs and tumor cells at distant sites might be attributed to a pro-apoptotic activity of B100 potentially mediated both by direct cellular effects and by the recruitment of immune (e.g., NK/CD4) cells." (PMID 32799890, 2020). "T lymphocytes transfected with the highest affinity MSLN-/--TCR (TCR1045) were able to bind MHC on target cells, independently from CD8 or CD4, displaying a higher lytic activity against PDAC MHC-I+ tumor cells compared to the highest affinity TCR from WT mice." (PMID 35582441, 2020). "Similar frequencies of CD3+, CD4+, and CD8+ T cells were found in draining lymph nodes from RANK+/+ and RANK−/− tumor transplants, but a moderate increase in IFNγ production in the lymph node T cells was observed in the RANK−/− tumor transplants." (PMID 33303745, 2020). "In addition, the levels of IFN-γ+-producing CD4+ or CD8+ T cells in splenocytes in vitro and IL-2 and IFN-γ in tumor tissues increased in the DTSP group." (PMID 32903495, 2020). "In ANPs plus RT group, CD4+ T/Tregs and CD8+ T/Tregs ratio were notably increased compared to control or RT alone, implying that can enhanced regional and systematic anti-tumor ability and improved tumor immune environment." (PMID 32408880, 2020). "Despite the comparable number of CD4+ T cells in inflammatory infiltration in normal and tumor tissues, a higher co-expression of PD-1 and CTLA-4 has been found in the T lymphocyte pool present in tumor tissues compared to control tissues." (PMID 32488850, 2020). "CLDN10 showed a positive correlation with the immune cells, such as CD4+T cells and macrophages, and a negative correlation with tumor purity." (PMID 32045884, 2020). "In contrast, the percentage of CD4+ T cells at the tumor sites in the AAV‐DNase I‐treated mice was not significantly different from those in the AAV‐null treated group." (PMID 32813937, 2020). "The immune reaction to antitumor was intensified by photodynamic therapy (PDT), where it effectively eradicated the tumor and remote metastasis in the B16-F10 melanoma model through encouraging cytokine production (TNF-α and IFN-ÿ) and tumor invasion lymphocyte frequency (CD8+ and CD4+)." (PMID 32865029, 2020). "Moreover, it was illustrated that the increase in proportions of effector and memory CD4+ and CD8+ T cells was not only in the tumor or tumor‐draining LNs, but also in spleen, showing that IRE increased the systematic infiltration of immune‐activated cells." (PMID 32508058, 2020). "Chlorine e6 and doxorubicin-loaded hollow manganese dioxide nano platform (H-MnO2-PEG/C&D) will alleviate tumor suppression, although checkpoint blocking (PD-L1 blocking) promotes higher TNF-α secretion and improved immune response of CD4 + and CD8 + T cells that chemo-PDT therapy." (PMID 32865029, 2020). "The ability for Yap-cKO CD4+ and CD8+ T cells to become activated and infiltrate tumors that normally inhibit T-cell infiltration is therefore remarkable and important, as these phenotypes are key for combating tumor growth in human cancer patients." (PMID 31929526, 2020).
tumor (continued). "Given the significantly poorer survival of immune-cold CRC patients, these data illustrate that assessment of CD4-expressing cells complements low CD3 and CD8 immunohistochemical quantification in the tumour bulk, potentially facilitating immunophenotyping of patient biopsies to predict prognosis." (PMID 32684627, 2020). "On the other hand, we cannot rule out that CD4+ Teff cells can potentially contribute to mediate tumor regression." (PMID 32099064, 2020). "The results of the correlation analyses showed that CD8+ T cells, CD4+ T cells, macrophages, neutrophils, and dendritic cells were positively correlated with the expression of ANTXR1, while they were negatively correlated with tumor purity." (PMID 33385012, 2020). "However, limited information is currently available on CD4 and CD8 single-positive T cells in TETs for anti-tumor immunotherapy." (PMID 32132638, 2020). "This approach was revealed to be an effective self-adjuvant delivery method since a single administration promoted antigen-specific CD4+ and CD8+ T cell proliferation and antibody responses, hampering tumor growth while increasing survival in breast cancer models." (PMID 32075343, 2020). "The in vivo anti-tumor effect was likely dependent on both CD4(+) T cells and CD8(+) T cells, as our serial IHC data did suggest a temporal sequence where the initial arrival of CD4(+) T cells was followed by subsequent infiltration of CD8(+) T cells." (PMID 33303017, 2020). "Furthermore, the expression level of CD16 on neutrophils in patients with capecitabine treatment was positively correlated with the number of anti-tumor immune cell subsets, such as CD8+T cell, CD4+T cell, NK cell and monocyte." (PMID 32770940, 2020). "IACS-010759 did not decrease CD45+ cells in spleen and tumor and total CD4+ and CD8+ T-cell percentages were not altered in tumor." (PMID 32581056, 2020). "We further observed patients with increased numbers of CD4+FOXP3+ T cells and CD8+ T cells in the tumor core have strong systemic immunity, which may be the mechanism of improved survival." (PMID 32377339, 2020). "Immunohistochemistry study revealed that the tumor cells were positive for CD4 and CD30, and were negative for cytokeratin, CD3, CD20, CD68, CD163, lysozyme, ALK, S-100, and desmin." (PMID 32547956, 2020). "Conversely, significantly higher infiltration of CD4+ T cells (median, 356 vs 308 cells/mm2, P < 0.0001) was noted in tumor liver tissues than non-tumor tissues." (PMID 33552954, 2020). "Additionally, high levels of IL-35 significantly increased the proportions of MDSCs and Tregs and decreased the proportions of CD4+ and CD8+ T cells in the spleen, blood and tumour microenvironment." (PMID 33041668, 2020). "However, within this group, tumor-bearing mice, which had similar levels of CD4+ T cells, had higher numbers of (activated) CD8+ T cells in the spleen compared to tumor-free mice." (PMID 32251475, 2020). "The combined PT immunoscore (CD8+, CD4+, and CD68) integrated with dNLR may be a promising marker for the development of an integrated Tumor, Node, Metastasis (TNM) immunoscore." (PMID 33072595, 2020). "This gave support to the idea that CD4+ Th cells were crucial in inducing the anti-tumor immune response, but not in acting as direct effectors against the tumor cells, in a similar way to CD8+ CTL." (PMID 33138029, 2020). "For example, CD20+, CD4+ and FoxP3+ lymphocytes were all significantly higher in the stromal compartment of the ER/PR negative tumours (all p < 0.03), and all four subtypes were similarly more prevalent at the tumour edge." (PMID 32577938, 2020). "Moreover, CD4+CD25+FoxP3+ Treg cells are capable of suppressing Th1 or Cytotoxic T lymphocytes responses and represent a major mechanism of tumor escape in several cancers." (PMID 33100273, 2020).
tumor (continued). "No major differences were observed within the CD4+ tumor-reactive TILs, which appeared to be primarily characterized by tumor necrosis factor (TNF) production only, and a smaller population releasing both IFNγ and TNF." (PMID 33198174, 2020). "Further colocalization experiments demonstrated that PTGDS was highly expressed in CD19+ B cells, CD4+ T cells and CD8+ T cells, suggesting that its protective effect may be enhanced by the anti-tumour effects of B cells and T cells." (PMID 32047563, 2020). "The stimulation of M1 macrophage will have the advantage of creating a perpetuating downstream effect through activation of cytotoxic killing of cancer cells through the activity of CD4+, CD8+ T cells, followed by phagocytosis by macrophage and multi-level suppression of tumor advancement." (PMID 32477352, 2020). "Furthermore, it was shown that down-regulation of the Ikaros leads to a reduction in CD4+ and CD8+ T cell percentages but augmented CD4+CD25+ Tregs in tumor-bearing (TB) mice." (PMID 33195038, 2020). "Importantly, the DPTs at the tumor sites expressed higher levels of PD-1, LAG-3, and TIM-3 than the CD4+ T cells, CD8+ T cells, Tregs, and naïve T cells." (PMID 32457755, 2020). "Maternal exposure to HFD did not significantly change E0771 tumor infiltration of CD4+ T lymphocytes or T reg cells (CD4+FOXP3+ cells) in the offspring." (PMID 32580156, 2020). "This highlights that non-Treg, hence potentially active CD4+ T cells; and PD-1+, most likely pre-existing tumor reactive CD8 T cells, are important immune subsets contributing to subsequent response to BCG treatment." (PMID 33584702, 2020). "Multivariate analysis revealed that the association of a high density of CD4+ T cells with unfavorable OS (HR = 1.480, 95% CI = 1.009 - 2.173, P = 0.045) was independent of AFP level, tumor size, tumor differentiation, microvascular invasion, and TNM stage." (PMID 33552954, 2020). "We analyzed the four types of CD4+ T cell proportions among UCC patients with different stages, different tumor differentiations and histology types; further, we analyzed the relationship between the four types of T cell frequencies and tumor vasoinvasion or lymph node metastases." (PMID 32552719, 2020). "In addition, TGF-β also inhibited the activity of CD4+ and CD8+ T cells, thereby facilitating the escape of cancer cells from T cell killing and the generation of a tumor microenvironment that blocks T cell action." (PMID 32328176, 2020). "Notably, the depletion of CD4+ cells significantly enhanced the effect of PDT + FlaB-Vax in local tumor control, suggesting rather tumor-promoting effect of CD4+ cell population." (PMID 33171765, 2020). "A rise in the number of CD4 and CD8 cells in tumours was reported." (PMID 33704184, 2020). "Regardless of absence of significant differences, the higher tumor infiltration of several immune cell types, such as CD8+ T and CD4+ T cells, was associated with better clinical outcomes in the young but not in the old age group." (PMID 32357420, 2020). "LAG 3 expression was correlated with CD4+ and CD8+ T-cells within the tumor (p < 0.001)." (PMID 32592066, 2020). "We also found that infiltrating CD4 and CD8 lymphocytes showed changes in markers of T cell activation and exhaustion upon repeated mCelyvir administration, suggesting continued activity of the tumor infiltrating T lymphocytes (TILs)." (PMID 32064039, 2020). "Another evidence of the ability of TNFα to impair the function of antitumor immune cells is that, in melanoma, the cytotoxic response against the tumor that is carried out by CD8+ T lymphocyte is inhibited by this cytokine, which is produced by CD4+ lymphocytes infiltrating the tumor." (PMID 32391269, 2020). "Furthermore, co-administration of Fbp1 knockdown and anti-pd-l1 antibody additively increased the tumor infiltration of CD45+CD8+ T and CD45+CD4+ T cells and a substantial reduction of CD11b+Gr1+ MDSCs." (PMID 31938049, 2020).
tumor (continued). "CXCL9, CXCL10, and CXCL11 were found to recruit CD4+ and CD8+ lymphocytes, while CXCL13 could specifically attract T regulatory and Th2 lymphocytes into the tumour microenvironment." (PMID 31913856, 2020). "However, when we measured the levels of CD4+ and CD8+ cells in the tumor, both decreased very rapidly after administering OXi4503." (PMID 32640548, 2020). "However, knocking out miR-21 in mice weakened proliferation of both CD4+ and CD8+ cells, reduced cytokine production and accelerated growth of grafted tumor via Pten/Akt pathway." (PMID 32019579, 2020). "Upregulation of PD‐L1, CD90, PDGFRβ, CD248 and Rgs5 which inhibit CD4+ and CD8+ cytotoxic T‐cell activity was reported in pericytes derived from within tumour microenvironments, which facilitates immunosuppression and eventual immune evasion of tumour cells." (PMID 32588948, 2020). "These experiments showed that activated CD4 T cells induce delayed type hypersensitivity (DTH)-like reactions and attract inflammatory cells (macrophages, granulocytes, eosinophils, and NK cells) in or around the tumor." (PMID 32630460, 2020). "In addition, IFN-γ upregulates expression of class II MHC, which in addition to presenting peptides to CD4+ T cells also is a ligand for the inhibitory receptor LAG-335,36 expressed by tumor antigen-specific CD8+ TILs37." (PMID 32001684, 2020). "In patients with resistance (i.e., progressive disease) to systemic PD-L1 checkpoint inhibitor monotherapy, subsequent intralesional IL2 therapy was able to induce a CR in 33% of patients with a potent increase in CD4+ and CD8+ cells from the tumor microenvironment infiltrate." (PMID 32455916, 2020). "Interestingly, the present study showed the presence of functional heterogeneity even in the same phenotypic populations of both CD4 T cells and CD8 T cells, and it was dependent on tumour grade." (PMID 32277125, 2020). "(A–C) Flow cytometry quantification of tumor infiltrating Tregs, CD4 (non-Treg) T-cells, and CD8eff T-cells." (PMID 31959281, 2020). "The relative proportions of CD8+, CD4+, CD4+FoxP3−, and CD4+FoxP3+ T cells in fresh tumour tissues were all independent of CRS (all p > 0.30)." (PMID 32418992, 2020). "Furthermore, the systemic delivery of NPsiCTLA‐4 increased the trafficking rate of both CD4+ and CD8+ T‐lymphocytes, with a decreased extension ratio for CD4+ FOXP3+ regulatory T cells, resulting in tumor growth inhibition." (PMID 32440473, 2020). "Furthermore, in the spleen and tumor tissues, the populations of CD8+ T cells and CD4+ Foxp3+ T cells were altered after DTSP vaccination." (PMID 32903495, 2020). "Treatment with nivolumab or pembrolizumab reduced the frequency of CD4+PD‐1hi cells in the blood and tumour tissue, but the effects on OS and PFS were not reported." (PMID 33015859, 2020). "In a proof of concept study in mice, the antitumoral activity of DNAhsp65 was correlated with increased percentages of activated lymphocyte (CD4/CD44hi, CD8/CD44hi) infiltration into the tumor mass, enhanced CD86 costimulatory molecule expression in APCs and CD8-T lymphocytes specific lysis." (PMID 35047886, 2020). "Having previously shown that SCARF1 mediates the specific recruitment of CD4+ T cells to LSEC in inflammatory conditions, we next explored whether it could play a role in the recruitment of TILs to the HCC tumor microenvironment." (PMID 34354939, 2020). "Moreover, the induction of CD4+ T-helper responses against tumor antigens is essential for sustained CD8+ T cell responses, can neutralize pre-existing CD4+ T-regulatory cells as well as orchestrate activation and immune attack by innate immune cells." (PMID 32358491, 2020). "Ablative RT combined with αPD-L1 mAb led to a significant increase in the number of CD8+ T cells expressing of IFNγ and Foxp3+ CD25+ expressing CD4+ T cells infiltrating into the tumor, but not into spleen or lymph nodes." (PMID 32287292, 2020).